NGF (nerve growth factor)
Diseases named in the same sentence as NGF in open-access papers (continued):
Sharing a sentence is not in itself a finding about the gene and the disease.
colon cancer (13 papers, 2014 to 2025). "The NGF/TrkA axis has also been implicated in the metastasis of various tumors, including breast cancer, lung cancer, colon cancer, pancreatic cancer, and prostate cancer." (PMID 38816365, 2024). "NGF has been associated with cancer cell proliferation as well as apoptosis of colon cancer cells and with angiogenesis." (PMID 27092172, 2016). "Next, Schwann cell-secreted NGF motivates the ERK signaling pathway in colon cancer cells, which augments the proliferation and migration of colon cancer cells and further increases the expression of exosomal miR-21-5p." (PMID 39981185, 2025). "We have previously reported that nerve growth factor (NGF) is upregulated in pancreatic, gastric, and colon cancers via neural inputs such as adrenergic and cholinergic." (PMID 40777309, 2025). "In colon cancer, researchers revealed that exosomal miR-21-5p, derived from cancer cells, enhances SC proliferation and migration by stimulating SCs to secrete nerve growth factor (NGF)." (PMID 39769484, 2024). "NGF derived from has been shown to activate the TrkA/ERK/ELK1/ZEB1 signaling pathway in colon cancer cells." (PMID 38816365, 2024). "The co-culture of Schwann cells with colon cancer cells promoted the proliferation and migration of colon cancer cells and Schwann cells, which was mediated by nerve growth factor (NGF) secreted from Schwann cells." (PMID 36522730, 2022). "The correlation in the expression between NGF and ZEB1 was determined by Pearson’s correlation, and ZEB1 was found to be positively correlated with NGF in colon cancer tissues from our cohort and the TCGA cohort." (PMID 36522730, 2022). "To explore how exosomes from colon cancer cells promoted the expression of NGF in Schwann cells, we analyzed the miRNA sequencing data of exosomes from the GEO database." (PMID 36522730, 2022). "In our study, NGF significantly increased the expression of phosphorylated TrkA in colon cancer cells." (PMID 36522730, 2022). "In summary, our data demonstrated that NGF increased ZEB1 expression in colon cancer cells through TrkA/ERK/ELK1." (PMID 36522730, 2022). "Meanwhile, the Schwann cells-derived NGF activated TrkA/ERK/ELK1/ZEB1 signaling pathway in colon cancer cells, which further enhanced the expression of exosomal miR-21-5p." (PMID 36522730, 2022). "Our data showed that NGF facilitated the proliferation, migration, invasion, and EMT of colon cancer cells, supporting the function of NGF in solid tumors." (PMID 36522730, 2022). "Our data showed that colon cancer cells augmented the expression of NGF in Schwann cells through exosomes, which in turn facilitated the progression of colon cancer." (PMID 36522730, 2022). "Both the mRNA and protein expression levels of NGF was found to be higher in colon cancer tissues from patients with T3 and T4 stage than in patients with T1 and T2 stage." (PMID 36522730, 2022). "Western blot, qRT-PCR, and ELISA assays showed that NGF expression was increased in Schwann cells when incubated with exosomes from colon cancer cells." (PMID 36522730, 2022). "In conclusion, our data demonstrated that colon cancer cells enhanced the proliferation and migration of Schwann cells by stimulating NGF secretion from Schwann cells." (PMID 36522730, 2022). "In our study, we found that colon cancer cells promoted the proliferation and migration of Schwann cells by stimulating the secretion of NGF from Schwann cells." (PMID 36522730, 2022). "Blocking TrkA suppressed the effect of NGF on the proliferation, migration, and invasion of colon cancer cells." (PMID 36522730, 2022). "Coincidently, miR-21-5p was positively associated with the expression of NGF, p-ERK, p-ELK1, and ZEB1 in human colon cancer tissues." (PMID 36522730, 2022). "ELISA assays indicated that the secretion of NGF was augmented in Schwann cells upon co-culture with colon cancer cells." (PMID 36522730, 2022).
colon cancer (continued). "In conclusion, our data demonstrated that Schwann cells facilitated the proliferation, migration, invasion, and EMT of colon cancer cells by secreting NGF." (PMID 36522730, 2022). "The expression and secretion of NGF in Schwann cells were elevated upon co-culture with colon cancer cells." (PMID 36522730, 2022). "In our study, we found that exosomal miR-21-5p derived from colon cancer cells promoted the expression of NGF in Schwann cells." (PMID 36522730, 2022). "Collectively, our data indicated that exosomal miR-21-5p derived from colon cancer cells induced the expression of NGF in Schwann cells." (PMID 36522730, 2022). "Inhibition of either NGF or miR-21-5p significantly inhibited the proliferation and metastasis of transplanted colon cancer cells in nude mice." (PMID 36522730, 2022). "Therefore, we detected the expression of ELK1 and cMYC in colon cancer cells upon treatment with NGF." (PMID 36522730, 2022). "Furthermore, inhibition of ERK phosphorylation or knockdown of ELK1 reversed the effect of NGF on the proliferation, migration, and invasion of colon cancer cells." (PMID 36522730, 2022). "Moreover, knockdown of ELK1 reversed the effect of NGF on the proliferation, migration, and invasion of colon cancer cells." (PMID 36522730, 2022). "Similarly, we found that NGF expression was elevated in Schwann cells both at mRNA and protein levels upon co-culture with colon cancer cells." (PMID 36522730, 2022). "NGF promotes ZEB1 expression in colon cancer cells through secretion of NGF." (PMID 36522730, 2022). "Also, inhibition of miR-21-5p in colon cancer cells suppressed the exosome mediated increase in NGF expression in Schwann cells." (PMID 36522730, 2022). "Our results implicated a reciprocal communication between colon cancer cells and Schwan cells that promoted the proliferation and metastasis of colon cancer, and identified NGF and exosomal miR-21-5p as potential therapeutic targets for the treatment of colon cancer." (PMID 36522730, 2022). "Moreover, Kaplan-Meier survival analysis indicated that colon cancer patients in the NGF-HIGH group had a shorter overall survival time than that in the NGF-LOW group in our cohort and TCGA cohort." (PMID 36522730, 2022). "Targeting NGF and exosomal miR-21-5p may be a potential therapeutic strategy for treating colon cancer." (PMID 36522730, 2022). "Moreover, we added recombinant human NGF to colon cancer cells at the same concentration as that secreted by Schwann cells when co-cultured with colon cancer cells." (PMID 36522730, 2022). "We used GNF5837, the inhibitor of TrkA, to evaluate whether NGF promoted the progression of colon cancer through TrkA." (PMID 36522730, 2022). "Next, we used TAT-Pep5, the inhibitor of p75, to examine whether p75 participated in NGF-induced proliferation and metastasis of colon cancer cells." (PMID 36522730, 2022). "Furthermore, colon cancer cells augmented NGF expression in Schwann cells through exosomes, forming a positive feedback loop." (PMID 36522730, 2022). "Furthermore, blocking NGF suppressed the progression of Schwann cell-induced progression of colon cancer." (PMID 36522730, 2022). "Moreover, blocking NGF significantly reversed the effect of colon cancer cells on the proliferative and migratory ability of Schwann cells." (PMID 36522730, 2022). "Also, inhibition of NGF or miR-21-5p significantly rescued the effect of Schwann cell co-culture on the volume and weight of subcutaneous colon tumors." (PMID 36522730, 2022). "Moreover, LY3214996, the inhibitor of phosphorylated ERK1/2, obviously reduced the effect of NGF on the proliferation, migration, and invasion of colon cancer cells." (PMID 36522730, 2022). "Thus, we detected the expression of ERK1/2 and AKT in colon cancer cells treated with NGF." (PMID 36522730, 2022). "Thus, we hypothesized that colon cancer cells might facilitate the secretion of NGF in Schwann cells through exosomes." (PMID 36522730, 2022).
colon cancer (continued). "Exosomal miR-21-5p released by colon cancer cells inhibited VHL expression in Schwann cells, which in turn stabilized the HIF-1α protein and increased the transcription of NGF." (PMID 36522730, 2022). "Thus, we wondered whether Schwann cells promoted the progression of colon cancer cells through NGF." (PMID 36522730, 2022). "The chi-square test identified that miR-21-5p was positively correlated with NGF, p-ERK, p-ELK1, and ZEB1 in the colon cancer specimens." (PMID 36522730, 2022). "In our study, we found that NGF obviously increased the phosphorylation of ERK and ELK1 in colon cancer cells through TrkA." (PMID 36522730, 2022). "Furthermore, the effects of the IRGs on colon cancer development remain unclear, although cancer progression has been linked to CD1B, XCL1, PLCG1, NGF, and OXTR." (PMID 32508884, 2020). "Inhibition of TrkA, but not p75, reversed the effect of NGF on the proliferation, migration, and invasion of colon cancer cells." (PMID 36522730, 2022). "NGF increased the expression of phosphorylated TrkA in colon cancer cells, but did not affect the expression of total TrkA and p75." (PMID 36522730, 2022). "In a chemically induced colon cancer model (Azoxymethane/Dextran sulfate sodium mouse inflammatory CRC model), overexpression of NGF in the colon epithelium resulted in the development of more and larger tumors, suggesting a potential role of NGF in CRC development." (PMID 37610689, 2024).
Hypertension (13 papers, 2019 to 2026). The presence of chronic increased pressure in the systemic arterial system. "Further studies also implicated increased expression of NGF in the vascular system as causing the development of sympathetic hyperinnervation resulting in hypertension." (PMID 30767081, 2019). "Our MR analysis showed that the increased level of beta-nerve growth factor (beta-NGF), which could be caused by Clenbuterol, could lead to a higher risk of hypertension." (PMID 37034613, 2023). "BDNF is related to cardiomyocyte contractility and its alterations with atherosclerosis and hypertension, and NGF plays a role in atrial autonomic OSAS-induced atrial fibrillation." (PMID 36982552, 2023). "Conversely, an administration of antiserum against NGF attenuates or prevents the development of hypertension and vascular hypertrophy concomitantly with reductions in sympathetic innervation and sympathetic neural activity in SHRs." (PMID 35284140, 2022). "According to the study results, a stronger NGF expression and a moderate NGF expression were detected in type I cells and in a subset of type II cells, respectively, in case of hypertension." (PMID 33019660, 2020). "Although NGF overproduction and its influences on the sympathetic nervous system have been shown in hypertensive animals, NGF status and its association with sympathetic nerve activity have not yet been explored in human hypertension." (PMID 35284140, 2022). "Therefore, it seems that in animal models NGF provides Janus-faced features mediating in one way the development of hypertension, and on the other hand, protecting against ischemia-induced injuries." (PMID 30767081, 2019). "Elevated plasma cortisol, recurrent discharges of individual sympathetic nerve fibers usually within a single cardiac cycle, and elevated tissue nerve growth factor are seen in both panic disorder and essential hypertension, which may be related to pathogenesis." (PMID 40153757, 2025). "In addition, our results suggest that NGF modulation might be a pharmacological target for interventions in sympathetic nerve hyperactivity which could promote hypertension and hypertension-related cardiovascular structural changes." (PMID 35284140, 2022). "Therefore, it could be hypothesized that abnormal synthesis and/or secretion of NGF could enhance sympathetic neural activity, potentially leading to the occurrences of hypertension and hypertensive cardiovascular damages." (PMID 35284140, 2022). "However, NGF status and its association with sympathetic nerve activity have not yet been explored in human hypertension." (PMID 35284140, 2022). "Elevated NGF may be involved in developing hypertension in SHR." (PMID 34627325, 2021). "Following the onset of hypertension (SHR bladder), markers such as HIF-1α, AT1, detrusor collagen, NGF, and TGF-β1/SMAD2/3 are upregulated, leading to increased fibrosis, reduced contractility, and decreased bladder capacity, while VEGF, MAS receptor (MASr), and antioxidants are decreased." (PMID 42162196, 2026). "According to these data, GDNF, together with other neurotrophins (NGF, BDNF, and NT-3), may have a role in both the onset and maintenance of hypertension, probably by the chemoreceptor-related stimulation of the sympathetic activity." (PMID 33019660, 2020).
metabolic syndrome (13 papers, 2010 to 2025). A cluster of metabolic risk factors for CARDIOVASCULAR DISEASES and TYPE 2 DIABETES MELLITUS. "NGF and its receptors are expressed in cells of the immunoendocrine axis implicated in the development of metabolic syndrome." (PMID 36768281, 2023). "HGF and NGF blood levels are elevated in obese subjects and are associated with the presence of metabolic syndrome and T2DM, and both molecules have been described as an inflammatory response protein made by adipocytes." (PMID 25159899, 2014). "Metabolic syndrome is associated with alterations in NGF levels." (PMID 36768281, 2023). "In fact, women with metabolic syndrome show high levels of NGF in plasma and subcutaneous adipose tissue." (PMID 36768281, 2023). "In the present work, we describe the multiple roles of NGF in immunoendocrine organs that are important in metabolic homeostasis and related to the pathophysiology of metabolic syndrome." (PMID 36768281, 2023). "NGF level in advanced atherosclerosis of the coronary wall was significantly lower than in controls and plasma level of NGF was reduced in patients with metabolic syndrome compared with controls." (PMID 30767081, 2019). "Among the subjects with sensory neuropathies, those with hyperesthesia exhibited a marked impairment in the glycemic control, dyslipidemia and a severely low level of NGF." (PMID 28841856, 2017). "A significant decrease in plasma NGF and BDNF was associated with the metabolic syndrome and atherosclerosis." (PMID 20181009, 2010). "Specifically, NGF levels are decreased in atherosclerotic coronary vascular tissue and a decrease in plasma NGF could be detected in metabolic syndrome patients." (PMID 25250333, 2014). "Specifically, NGF and BDNF levels are significantly altered in metabolic syndrome and also in stress conditions." (PMID 29375393, 2017).
polycystic ovaries (13 papers, 2006 to 2022). "It cannot be discarded that fertility disorders like polycystic ovary, or others associated with impaired angiogenesis have a genesis in a deregulation of NGF expression or function that results in aberrant production of VEGF." (PMID 17096853, 2006). "Interestingly, an increasing number of studies are providing evidence to show that NGF is associated with ovarian diseases, such as polycystic ovary syndrome (PCOS)." (PMID 29580253, 2018). "The administration of estradiol valerate (a polycystic ovary [PCO] phenotype model) increased norepinephrine (NE) (through an NGF-dependent mechanism) and acetylcholine (ACh) levels." (PMID 33716987, 2021). "NGF has also been described as an etiological factor in the development of polycystic ovary phenotype in rat and mouse." (PMID 31024331, 2019). "Excessive nerve growth factor (NGF) is commonly found in the follicular fluid of patients with polycystic ovary syndrome (PCOS)." (PMID 29580253, 2018). "In a rat model of polycystic ovaries induced by estradiol valerate, ginseng normalizes ovarian morphology, reduces antral follicle counts, and increases corpus luteum numbers via regulation of nerve growth factor expression." (PMID 35067219, 2022). "Moreover, human and animal studies have demonstrated an association between increased intra-ovarian synthesis of nerve growth factor (NGF) and polycystic ovaries." (PMID 30410448, 2018). "An elevation of ovarian NGF and p75 is observed in rats with steroid-induced polycystic ovaries, and the intraovarian administration of a neutralizing antiserum to NGF in conjunction with an antisense to p75 normalized estrous cyclicity and ovulatory capacity in a majority of the animals." (PMID 17096853, 2006). "Stener-Victorin reported that repeated EA stimulation significantly promoted the release of β-endorphins in the hypothalamus of polycystic ovary (PCO) rats and reduced nerve growth factor (NGF), corticotropin-releasing factor (CRF), and endothelin-1 (ET-1) in the ovaries of PCO rats." (PMID 35832528, 2022).
type 2 diabetes (13 papers, 2010 to 2025). "In recent clinical study data of healthy and type 2 diabetes patients, diagnostic values of BDNF and NGF showed high sensitivity and specificity with very good AUC values." (PMID 35626286, 2022). "In previous studies, it was found that the ability of SCs to secrete the neurotrophic factors NGF and NT-3 is significantly decreased in murine models of both type 1 and type 2 diabetes." (PMID 36291547, 2022). "Previously, we have reported that there is increased NGF expression in dermal inflammatory cells and nerve fibers in db/db mice, indicating that similar NGF-mediated inflammation occurs in the skin of mice with type 2 diabetes." (PMID 20482876, 2010). "Furthermore, combining LIPUS with tadalafil effectively treats erectile dysfunction in patients with type 2 diabetes, and promotes nerve regeneration and improves erectile function by enhancing Schwann cell proliferation, migration, and expression of neurotrophic factors such as nerve growth factor." (PMID 37732128, 2023). "A multicenter phase-three study in 1019 patients with type 1 or type 2 diabetes and DPN assessed the effects of recombinant NGF (rhNGF) 0.1 mcg/kg (n = 504) or placebo (n = 515) subcutaneously three times per week over 48 weeks." (PMID 35328284, 2022).
amyotrophic lateral sclerosis (12 papers, 2012 to 2024). Amyotrophic lateral sclerosis (ALS) is a neurodegenerative disease characterized by progressive muscular paralysis reflecting degeneration of motor neurons in the primary motor cortex, corticospinal tracts, brainstem and spinal cord. "NGF antagonists have also demonstrated positive results after spinal cord injury, or amyotrophic lateral sclerosis (ALS)." (PMID 28273811, 2017). "To date, the potential beneficial effect of neurotrophins, NGF and BDNF, in particular, have been explored in light of several neurodegenerative disorders, including but not limited to AD, Amyotrophic lateral sclerosis (ALS), Huntington disease, Parkinson’s Disease and even obesity." (PMID 23210531, 2012).